SALL4 (spalt like transcription factor 4)
Diseases named in the same sentence as SALL4 in open-access papers (continued):
Sharing a sentence is not in itself a finding about the gene and the disease.
acute myeloid leukemia (26 papers, 2009 to 2025). Acute myeloid leukemia (AML) is a group of neoplasms arising from precursor cells committed to the myeloid cell-line differentiation. "In human acute myeloid leukemia, the expression of SALL4 is associated with cancer progression and predictive of treatment outcomes." (PMID 32513235, 2020). "High levels of SALL4 have been reported in acute myeloid leukemia (AML), liver cancer, colon cancer, breast cancer, endometrial cancer, lung cancer, and gliomas." (PMID 41163374, 2025). "SALL4 is a tumour stem cell marker found in acute myeloid leukaemia and is involved in the proliferation and migration of a variety of tumour cells." (PMID 36316684, 2022). "Expression of SALL4 in some subtypes of leukemias such as precursor B-cell lymphoblastic leukemia and acute myeloid leukemia demonstrates activation of different molecular machineries in B- and T-cell lymphoblastic leukemias." (PMID 36010677, 2022). "In addition, a significant increase in cell apoptosis is frequently observed in SALL4-deficient cells of acute myeloid leukemia, esophageal squamous cell carcinoma and endometrial cancer, which may also account for the growth suppression mediated by SALL4 knockdown." (PMID 32513235, 2020). "Previous studies have shown that aberrant hypomethylation in SALL4 promotor is strongly correlated with SALL4 upregulation in myelodysplastic syndromes and acute myeloid leukemia." (PMID 32513235, 2020). "SALL4 was aberrantly expressed in many leukemia cell lines and primary leukemia cells of acute myeloid leukemia (AML) and precursor B-cell lymphoblastic leukemia/lymphomas." (PMID 31653163, 2019). "This study aimed to characterize the expression pattern of SALL4 gene in adult patients with acute myeloid leukemia." (PMID 31653163, 2019). "SALL4 gene was aberrantly expressed in many leukemia cell lines and primary leukemia cells of acute myeloid leukemia (AML) and precursor B-cell lymphoblastic leukemia/lymphomas." (PMID 31653163, 2019). "SALL4 was firstly described in leukemogenesis, with constitutive expression in human acute myeloid leukemia." (PMID 27329034, 2016). "Using immunohistochemistry and real-time PCR, SALL4 was demonstrated to be constitutively expressed in human primary acute myeloid leukemia." (PMID 23067006, 2012). "SALL4 is constitutively expressed in human leukemia cell lines and primary acute myeloid leukemia (AML) cells." (PMID 23067006, 2012). "Furthermore, SALL4 is aberrantly expressed in human acute myeloid leukemia, and transgenic SALL4 mice develop acute myeloid leukemia." (PMID 21526180, 2011). "Moreover, we have reported that SALL4 is constitutively expressed in human leukemia cell lines and primary acute myeloid leukemia (AML) cells." (PMID 19440552, 2009). "The expression of SALL4 increases in acute myeloid leukemia (AML), liver cancer, breast cancer, endometrial cancer, lung cancer, and glioma." (PMID 35692499, 2022). "On the other hand, methylation-specific PCR (MSP) has validated aberrant hypomethylation of SALL4 promoter in acute myeloid leukemia (AML) and myelodysplastic syndrome (MDS) patients." (PMID 36010677, 2022). "Hypomethylation of the promoter region of SALL4 has been observed in myelodysplastic syndrome (MDS) and acute myeloid leukemia (AML) and is strongly associated with high mRNA levels of SALL4." (PMID 33644042, 2021). "SALL4 has been first reported to be abnormally expressed in human acute myeloid leukemia (AML) and regulate survival and apoptosis of leukemic cells." (PMID 32719361, 2020). "Pharmacological peptides that specifically disrupt the interaction between SALL4 and HDAC1 have been tested with success as therapeutic agents both in acute myeloid leukemia and hepatocarcinoma." (PMID 38062245, 2024). "Initially, a 12-AA peptide developed by our group that effectively blocked the interaction between SALL4 and NuRD complex in HCC and acute myeloid leukemia." (PMID 36010677, 2022).
acute myeloid leukemia (continued). "Additionally, SALL4 is directly bound to β-catenin, which activates the Wnt pathway in AML (acute myeloid leukemia)." (PMID 34944911, 2021). "SALL4 transgenic mice develop MDS prior to acute myeloid leukemia (AML) transformation." (PMID 24283704, 2013). "While most other studies have not distinguished between isoforms, SALL4 mutations that affect both isoforms are implicated in the human Duane-Radial Ray syndrome and acute myeloid leukemia (AML)." (PMID 21776282, 2011). "Furthermore, induction of SALL4 expression in murine models can induce myelodysplastic syndrome (MDS) and progression to Acute Myeloid Leukemia (AML), demonstrating that SALL4 re-expression had oncogenic function." (PMID 34573282, 2021). "In primary acute myeloid leukemia (AML) and myelodysplastic syndrome (MDS), the expression of SALL4 is higher than health control." (PMID 24860834, 2014). "Although downregulated or absent in most adult tissues, abnormal SALL4 expression has been detected in various human tumors and leukemias which include acute myeloid leukemia (AML), B-acute lymphoblastic leukemia, and chronic myeloid leukemia (for a review, see Ref." (PMID 28974232, 2017).
lung carcinoma (25 papers, 2013 to 2025). "SALL4 expression is upregulated in EGFR-mutated lung cancer cells, which promoting lung cancer cells from invading and metastasizing." (PMID 38355684, 2024). "Previous research has linked high SALL4 expression to a more sensitive response to entinostat treatment in human lung cancer cells." (PMID 37525212, 2023). "Activation of SALL4 in EGFR mutated lung cancer cells resulted in spheroid formation and expression of stem cell factor CD44." (PMID 36010677, 2022). "SALL4 is overexpressed in diseases such as cervical cancer and lung cancer and is associated with enhanced tumorigenesis and tumor progression." (PMID 34455417, 2021). "In this study, we show that depletion of SALL4 by shRNA resulted in a decreased in cell viability and tumorigenicity of SALL4-positive lung cancer cells, which were associated with dysregulation of both EGFR and IGF1R signaling pathways." (PMID 27705911, 2016). "A previous study showed that SALL4 expression is abnormally high in lung cancer, indicating that a deep understanding of the function underlying the progression and prognosis of lung cancer involved in SALL4 is critical for promoting an early diagnosis and effective therapy." (PMID 35216168, 2022). "SALL4 aberrant expression is observed in lung cancer patients with poor survival and it is shown to be a good diagnostic marker with 88% sensitivity and 100% specificity in lung cancer patients." (PMID 36010677, 2022). "Finally, our results strongly indicated the EGFR activation could specifically induce the expression of SALL4 in lung cancer and also suggest a positive association between SALL4 expression and EGFR mutation." (PMID 29691367, 2018). "AJAY considered that SALL4 may be an extremely useful diagnostic marker in lung cancer." (PMID 28887597, 2017). "Furthermore, it is proposed that SALL4 may have diagnostic and therapeutic value in breast and lung cancers." (PMID 23363002, 2013). "Therefore, SALL4 can be detected with high sensitivity and specificity and may have diagnostic and therapeutic value in breast and lung cancers." (PMID 23363002, 2013). "Existing research has indicated that SALL4 expression is correlated with chemoresistance in breast and lung cancers." (PMID 41340257, 2025). "Lung cancer cell lines expressing high levels of SALL4 are sensitive to the HDAC1 inhibitor Entinostat suggesting the use of this drug as a potential treatment for lung cancer." (PMID 38062245, 2024). "The ATP synthase inhibitor oligomycin reduced the viability of HCC and lung cancer cells with high SALL4 expression." (PMID 35216168, 2022). "Downregulation of SALL4 inhibits cell proliferation, clonal formation, migration, and invasion of lung cancer while promoting cell arrest in the G0/G1 phase by inhibiting the expression of cell cycle-related proteins such as cyclin B, cyclin D1, and cyclin E." (PMID 35216168, 2022). "More experimental studies showed that SALL4-high lung cancer cells are more vulnerable to Entinostat treatment." (PMID 36010677, 2022). "High SALL4 expression resulted in proliferative, invasive, and anti-apoptotic effects in lung cancer through activation of PI3K/AKT/mTOR signaling." (PMID 35216168, 2022). "Similar to other cancer types, overexpression of SALL4 is observed in chemotherapy-resistant lung cancer cells." (PMID 36010677, 2022). "SALL4 is involved in activation of resistant mechanisms post adjuvant-chemotherapy and knockdown of the gene results in sensitivity of lung cancer cells to platinum-based drugs." (PMID 36010677, 2022). "Our result affirms previous findings regarding the association between SALL4 overexpression and cell proliferation using SBC-1 lung cancer cells." (PMID 34441397, 2021). "The study used a panel of 17 lung cancer cell lines with varied SALL4 expression levels, showing that cells expressing high levels of SALL4 were more sensitive to Entinostat treatment." (PMID 34944911, 2021).
lung carcinoma (continued). "As another example, the knockdown of SALL4 (identified in all tissues) in cancer cell lines has been shown to increase the sensitivity of lung cancer cells and esophageal squamous cell carcinoma cells to cisplatin." (PMID 31967990, 2020). "SNHG4 acted as a sponge for miR-98-5p, which can directly target CDK6 and SALL4, and SALL4 is upregulated in lung cancer tissues." (PMID 33412752, 2020). "More interestingly, the SALL4 expression in EGFR-mutant lung cancer was significantly higher than that in lung cancer tissue with wild-type EGFR." (PMID 29691367, 2018). "Our results indicate that SALL4 expression is associated with EGFR mutation and SALL4 inhibition can increase the sensitivity of EGFR TKIs in lung cancer." (PMID 29691367, 2018). "All in all, these results suggest that SALL4 is involved in inhibiting the spheroid formation capacity and reducing the expression of lung cancer stem cell markers and pluripotency transcriptional factors." (PMID 29691367, 2018). "In this study, we not only demonstrated that SALL4 was highly in lung cancer tissues, but also found that aberrant expression of SALL4 was associated EGFR mutation in NSCLC was essential for the cell stemness of EGFR mutant-driven NSCLC cells." (PMID 29691367, 2018). "The unique expression pattern of SALL4 in lung cancer suggests that it can potentially be a good drug target for personalized medicine, targeting the lung cancer subtypes that cannot be treated by current targeted therapies like EGFR and ALK inhibitors." (PMID 27705911, 2016). "In our present study, we further evaluated the anti-proliferative effects of this 12-amino acid peptide in SALL4-expressing lung cancer cell lines." (PMID 27705911, 2016). "A panel of 17 lung cancer cell lines with different expression levels of SALL4 was evaluated for their drug sensitivity to entinostat." (PMID 27705911, 2016). "We first noticed that lung cancer cells with high SALL4 expression levels such as H661 and PC-9 cells were more sensitive to entinostat treatment than those with low SALL4 expression level, such as H1299 cells." (PMID 27705911, 2016). "A separate SALL4 gene signature generated from differentially expressed genes following SALL4 knockdown in the lung cancer cell line H661 was also used by cMap." (PMID 27705911, 2016). "In our case, the drugs that received a score close to -1 are most likely to have therapeutic values for the SALL4-expressing lung cancer cells since the drug signatures are in a reverse correlation with the SALL4 gene signature." (PMID 27705911, 2016). "A negative correlation between the IC50 of entinostat and SALL4 expression level was observed, suggesting that lung cancer cells with high SALL4 expression were more sensitive to entinostat treatment (P = 0.03)." (PMID 27705911, 2016). "Next, to investigate the functional role of SALL4 in lung cancer, SALL4 expression was downregulated by lentiviral-mediated delivery of SALL4-specific short hairpin RNA (shRNA) to the high SALL4-expressing lung cancer cell lines (H661, H522, H292 and PC-9)." (PMID 27705911, 2016). "SALL4 silencing by RNA interference or SALL4 peptide inhibitor treatment led to impaired lung cancer cell growth." (PMID 27705911, 2016). "This lays the foundation for future clinical studies evaluating the therapeutic efficacy of entinostat in SALL4-positive lung cancer patients." (PMID 27705911, 2016). "Connectivity Map analysis revealed the HDAC inhibitor entinostat as a potential drug in treating SALL4-expressing cancers, and this was confirmed in 17 lung cancer cell lines." (PMID 27705911, 2016). "Taken together, these data suggest that SALL4 has a functional role and is a feasible drug target in lung cancer." (PMID 27705911, 2016). "Entinostat can induce the expression of CBLB, a gene that is repressed by SALL4 in lung cancer cells, representing a potential mechanism for the sensitivity of SALL4-expressing lung cancer cells to this drug." (PMID 27705911, 2016).
lung carcinoma (continued). "While we have identified a peptide to specifically inhibit the growth of SALL4-expressing lung cancer cells, the clinical utility of peptides, in general, is limited by their sub-optimal in vivo delivery efficiency." (PMID 27705911, 2016). "Similar observation was also seen in another cohort of samples from the GEO database – elevated SALL4 expression is observed in lung cancer patients (Accession GSE19188)." (PMID 27705911, 2016). "Using a panel of 17 lung cancer cell lines with varying SALL4 expression levels as a preclinical model, we further confirmed that high SALL4 expression lung cancer cells were more sensitive to entinostat treatment." (PMID 27705911, 2016). "The observation that SALL4 is overexpressed in a subgroup of lung cancers was further validated by analysis of published gene expression profiles of lung cancers in public databases." (PMID 27705911, 2016). "To investigate if SALL4 has a functional role in tumorigenicity of lung cancer cells, we first screened 16 NSCLC cell lines for SALL4 expression by using qRT-PCR in order to select for appropriate models for downstream functional studies." (PMID 27705911, 2016). "The correlation between SALL4 expression and poorer patient survival in lung cancer is consistent with our observations from HCC, endometrial cancer and myelodysplastic syndrome." (PMID 27705911, 2016). "We herein report that SALL4 was aberrantly expressed in a subset of lung cancer patients with poor survival." (PMID 27705911, 2016). "Aberrant SALL4 expression in lung cancer patients has been reported, and the detection of SALL4 mRNA expression has been proposed as a diagnostic marker for lung cancer patients." (PMID 27705911, 2016). "We observed elevated SALL4 expression in a subset of lung cancer patients compared to normal lung tissues." (PMID 27705911, 2016). "In our present study, we first examined SALL4 expression in a cohort of primary lung cancer samples using immunohistochemical staining." (PMID 27705911, 2016). "We have evaluated SALL4 expression in lung cancer in large cohorts of patients, and observed that SALL4 expression is upregulated in a subset (about 16%) of these patients including EGFR mutation negative cases." (PMID 27705911, 2016). "We first performed cMap analysis using one set of SALL4 gene signature generated from the comparison between normal human control versus primary lung cancer samples." (PMID 27705911, 2016). "Overall, our studies suggest that targeting SALL4 by entinostat is a novel approach for lung cancer treatment." (PMID 27705911, 2016). "Seven of these 12 lung cancer patients had increased SALL4 expression, and overall, there was a statistically significant increase in SALL4 expression in lung cancer tissues as compared to adjacent normal lung tissues (P=0.04)." (PMID 27705911, 2016). "To elucidate the potential mechanism(s) of SALL4 in lung cancer, we performed microarray gene expression profiling on H661 cells treated with scramble shRNA control and a SALL4-specific shRNA." (PMID 27705911, 2016). "siRNA-mediated SALL4 inhibition led to inhibition of lung cancer cell proliferation that was induced by cell cycle arrest at the G1/early S phase." (PMID 26317546, 2015). "SALL4 can also interact with miRNAs in lung cancer, including miR-250 and miR-3619." (PMID 35216168, 2022). "SALL4 regulates the progression of lung cancer through several mechanisms, and it may have a close correlation with drug resistance." (PMID 35216168, 2022). "Moreover, transducing lung cancer cells with siRNA against SALL4 resulted in more sensitivity of the cells to platinum-based drugs." (PMID 36010677, 2022). "Furthermore, knockdown of SALL4 can restore cisplatin sensitivity in acquired resistant lung cancer cells via the AKT/mTOR signaling pathway, and the antineoplastic drug entinostat can target SALL4-positive lung cancer." (PMID 35216168, 2022). "Knock down studies support the importance of SALL4 in progression of lung cancer." (PMID 36010677, 2022).